MTOR (mechanistic target of rapamycin kinase)
Diseases named in the same sentence as MTOR in open-access papers (continued):
Sharing a sentence is not in itself a finding about the gene and the disease.
kidney tumors (continued). "While TSC/MTOR mutation-associated renal tumors share common pathway alterations, the type of mutation and the cell of origin may influence their biology and clinical behavior." (PMID 37627070, 2023). "Moreover, loss of chromosome 1 was identified in the four renal neoplasms and the skull and liver metastases, which represents the genomic location of the mTOR gene." (PMID 37938323, 2023). "Finally, case 3 showed pathogenic mTOR alterations in both the primary renal tumor and the liver metastases involving the exon 53 (p.Leu2427Gln—COSM1185313)." (PMID 37938323, 2023). "FH-deficiency may activate the proto-oncogene ABL1 in kidney tumors, which may upregulate aerobic glycolysis via the mTOR/HIF1α pathway, being a promising target marker." (PMID 27556703, 2016). "This study reinforces the notion that LOT is a distinct renal tumor entity with consistent morphology, immunoprofile, and mTOR-pathway-related genetic alterations." (PMID 40584698, 2025). "Herein, we discuss renal tumors with frequent TSC/mTOR pathway gene alterations in both the germline and sporadic settings." (PMID 37627070, 2023). "mTOR inhibitors such as rapamycin and everolimus have shown efficacy in reducing the renal tumor burden." (PMID 35814396, 2022). "Recently, comprehensive genomic analyses have described the relative frequency of tuberous sclerosis complex 1 and 2 (TSC1/TSC2) gene mutations, drawing attention to the role of the mammalian target of the rapamycin (mTOR) pathway in different renal tumors." (PMID 34069976, 2021). "A separate subtype of renal tumors characterized by eosinophilic cells and mutations in the TSC/mTOR pathway is emerging." (PMID 34069976, 2021). "The AKT/mTOR signaling cascade activation was found in the primary kidney tumor, both localized and disseminated cancers." (PMID 34563045, 2021). "Early clinical trials show that kidney tumours regress in response to treatment with rapamycin and other mTOR inhibitor including everolimus, a direct-target of inhibition of mTORC1." (PMID 30250638, 2018). "Prolonged feeding of a ketogenic diet promotes the growth of renal tumors by recruiting ERK1/2 and mTOR which are associated with the accumulation of oleic acid and the overproduction of growth hormone." (PMID 26892894, 2016). "PKM2 expression was augmented in mouse kidney tumors and consequent mTOR activation, and was reduced by mTOR suppression." (PMID 27916907, 2016). "PKM2 expression increased in mouse kidney tumors with loss of TSC2 and activation of mTOR, but decreased in human cancer cells with reduced mTOR activity." (PMID 22680924, 2012). "The dual PI3K/mTOR inhibitor (NVP-BEZ-235) was used to treat ENU-accelerated kidney tumors in the Tsc2+/- mouse." (PMID 20146790, 2010). "Hereditary loss leads to an increased incidence of several tumor types, including kidney tumors.The TSC tumor suppressors are key components in the upstream regulation of mTOR." (PMID 19860903, 2009). "Here, we explore the potential benefit of the mTORC1 inhibitor RAD001 (everolimus) in comparison to a dual pan-class I PI3K/mTOR catalytic inhibitor NVP-BEZ-235 in the therapy of Tsc2 mouse kidney tumors." (PMID 19527517, 2009). "We conclude that evaluation of the ‘caveolin-1/AKT/mTOR axis’ in primary kidney tumours will identify subsets of RCC patients who require greater postoperative surveillance and more intensive treatment." (PMID 18283322, 2008). "Although mTOR inhibitors, such as everolimus, have shown a beneficial effect in BHD patients, more clinical studies are needed to evaluate its efficacy of it in BHD-associated renal tumors." (PMID 35479937, 2022). "ESC RCC adds to the spectrum of renal neoplasms associated with alterations in TSC genes and mTOR pathway, which may have consequences for the selection of specific targeted treatments (such as mTOR inhibitors)." (PMID 34680535, 2021). "The AKT/mTOR signaling cascade activation was found in the primary kidney tumors." (PMID 32668608, 2020).
kidney tumors (continued). "Since LPA mediates its effects via GPCRs to activate multiple intracellular signaling pathways including AKT/mTOR, we next assessed whether addition of LPA alters the AKT/mTOR pathway in a malignant renal tumor cell line." (PMID 32492043, 2020). "Previously, it was reported that the amount of PDGFRα could also be decreased in kidney tumors, while the amount of mTOR is increased and mTOR signaling is upregulated." (PMID 27293550, 2016). "Interestingly, it has been shown that Notch signaling is dependent on mTOR in lung and kidney tumor cells, indicating the existence of a positive feedback loop between Notch and EGFR signaling." (PMID 27118928, 2016). "However, since inactivation of the Tsc2 and folliculin genes in mice have been associated with the development of renal tumours and mammalian target of rapamycin (mTOR) disregulation, we investigated the OTA-associated tumours for evidence of mTOR activation." (PMID 23105973, 2012). "We have previously used Tsc2+/- mice in a C57BL/6 mixed strain to show that mTOR inhibitor treatment reduces kidney tumor severity, to investigate the timing of mTOR inhibitor treatment, and to show that addition of prolonged weekly maintenance rapamycin treatment was extremely effective." (PMID 20146790, 2010). "In addition we evaluated the phophorylation level of downstream targets of mTOR, phospho-S70K, in kidney tumor tissue from TSC patients." (PMID 19265534, 2009). "Concurrently, the current literature showed the presence of mTORC1 pathway alteration (TSC1/TSC2/mTOR/RHEB) in a number of recently described renal tumors in patients without TSC mutations (i.e., in sporadic tumors in patients without germinal mutation of TSC1 or TSC2)." (PMID 35203531, 2022). "In addition, the renal tumors from BHD patients showed increased phosphorylation of mTOR." (PMID 20573232, 2010). "Finally, we examined whether mTOR inhibition via Torin1 reduced kidney tumor burden in STP mice." (PMID 41044182, 2025). "Recent published data from our laboratory show that significant inhibition of mTOR by rapamycin and activation of AMPK by AICAR in several kidney tumor cells isolated from TSC2+/− mouse model." (PMID 30250638, 2018). "In this study, we identified mTOR as a stimulator of PGAM1 expression in cell lines, Tsc2 mutant mouse kidney tumor sample and human NSCLC tissues." (PMID 29362480, 2018). "The present study was conducted to investigate the effect of tuberin deficiency on phosphorylation of S6Kinase (downstream targets of mTOR) and on OGG1 expression and 8-oxodG levels in kidney tumors from TSC patients." (PMID 19265534, 2009). "Furthermore, viaGLUD1 inhibits kidney tumor occurrence and development by suppressing the PI3K/Akt/mTOR pathway, while LINC00460 promotes RCC development by affecting the PI3K/AKT pathway and decreasing the phosphorylation levels of AKT and mTOR." (PMID 38110984, 2023). "However, since the survey was conducted, an emerging marker, GPNMB, appears to show promise for recognizing renal neoplasms with MITF family translocations and TSC/MTOR pathway alterations, which was not assessed in this study." (PMID 39287823, 2024).
medulloblastoma (42 papers, 2010 to 2025). A malignant, invasive embryonal neoplasm arising from the cerebellum. "The aberrant activation of the Hedgehog (HH) pathway along with the PI3K/mTOR pathway is frequently implicated in high-risk medulloblastoma." (PMID 37568705, 2023). "The literature is deficient in mTOR involvement in medulloblastoma and mTOR inhibitor resistance, with mTOR having potential as a chemotherapeutical agent for medulloblastoma." (PMID 35008889, 2021). "Aberrant activation and interactions of hedgehog (HH) and PI3K/AKT/mTOR signaling pathways are frequently associated with high-risk medulloblastoma (MB)." (PMID 29682173, 2018). "Against this background, we have previously shown that upstream of mTOR/AKT the clinically available PI3K inhibitor GDC‐0941 potently inhibits AKT phosphorylation in high‐risk variants of medulloblastoma and promotes survival in an orthotopic xenograft model." (PMID 29377550, 2018). "Interestingly, studies by us and others have shown that mTOR signaling is overactivated in Group 3 (MYC-amplified) medulloblastoma, suggesting association between MYC and mTOR in medulloblastoma." (PMID 39779613, 2025). "This would suggest that our high frequency MB mouse model Ptch1+/−/Tis21KO, carrying activation of both the Shh and the PI3K/AKT/mTOR pathways, could be a model representative of such a cohort of patients with high-risk Shh-type medulloblastoma." (PMID 34395258, 2021). "Clinical trials have been conducted to evaluate the use of mTOR inhibitors, like rapamycin and its analogs, in treating medulloblastoma." (PMID 39779613, 2025). "It is important to note that the role of mTOR signaling in medulloblastoma can vary between individual cases and molecular subgroups." (PMID 39779613, 2025). "A combination of CDK and mTOR inhibitors holds potential for controlling MYC-amplified medulloblastoma." (PMID 39779613, 2025). "The interaction between MYC and mTOR signaling pathways can create a robust network of resistance to therapy in medulloblastoma." (PMID 39779613, 2025). "Recently, a combination of ribociclib with bet-bromodomain and PI3K/mTOR inhibitors was used for medulloblastoma treatment." (PMID 39779613, 2025). "MTOR signaling-driven deregulated protein synthesis is widespread in various cancers, including medulloblastoma, which can promote the stabilization of MYC." (PMID 39779613, 2025). "Combination therapy targeting MYC (by BET inhibition) and mTOR signaling proved efficacious against medulloblastoma." (PMID 39779613, 2025). "The activation of mTOR pathway has been shown to be involved in such resistance in cancers, including medulloblastoma." (PMID 39779613, 2025). "This review explores concurrent targeting of MYC and mTOR signaling against MYC-driven medulloblastoma." (PMID 39779613, 2025). "Our studies evaluated the anti-cancer potential of combined inhibition of MYC transcription and mTOR signaling in MYC-amplified medulloblastoma." (PMID 39779613, 2025). "This work holds the promise of significantly advancing our understanding of MYC-driven oncogenesis and provides critical preclinical data essential for the development of novel therapies targeting CDK8 and mTOR in MYC-driven medulloblastoma." (PMID 39574899, 2024). "Another miRNA that comprises a potential target is the pro-tumorigenic and pro-metastatic miR-183~96~182 complex, which was found to be upregulated in MYC-amplified medulloblastomas and to be an upstream inducer of PI3k/mTOR signaling." (PMID 37568705, 2023). "Medulloblastomas and other malignant brain tumors are often associated with genetic mutations and epigenetic modifications that activate the PI3K/AKT/mTOR signaling pathway." (PMID 37568705, 2023). "A most recent study reveals that the activity of the mTOR pathway is strongly attenuated in DHODH-knockout medulloblastoma SU_MB002 cell lines, thereby inducing cell-cycle arrest and apoptosis." (PMID 36672495, 2023).
medulloblastoma (continued). "Another team has also shown the role of the perivascular niche in resistance to radiation in medulloblastoma through the activation of the Akt/mTOR pathway in perivascular nestin-expressing stem cells." (PMID 36430649, 2022). "This systematic review highlights the mechanisms of resistance of mTOR inhibitors in medulloblastoma and includes IDO1, T cells, Mnk2, and eIF4E, as they prolong malignant cell survival." (PMID 35008889, 2021). "Only a few mTOR inhibitors have been investigated for the treatment of medulloblastoma and other pediatric tumors." (PMID 35008889, 2021). "Because non-MYCN-amplified NB cell lines, including SK-N-AS, express MYC which is a target for combined BET/mTOR in medulloblastoma cells." (PMID 34565342, 2021). "We demonstrate mTOR pathway activation and metabolic adaptation specifically in medulloblastoma of the molecular subgroup G4 characterised by a BMI1High;CHD7Low signature and show this can be counteracted by IP6 treatment." (PMID 33846320, 2021). "The mechanistic target of rapamycin (mTOR) is one of the major pathways that have been activated during medulloblastoma development." (PMID 35008889, 2021). "Beyond NB, this therapeutic approach can be of broader relevance for therapy of MYC/MYCN-addicted cancers, as we have previously shown a synergistic antitumor efficacy of BET/mTOR inhibitors in MYC-driven medulloblastoma." (PMID 34565342, 2021). "There is a gap of knowledge relevant to the mechanism of resistance of mTOR inhibition in medulloblastoma." (PMID 35008889, 2021). "Consistent with this, dual inhibition of the phosphatidylinositol 3-kinase (PI3K)/mTOR and HH pathways has been shown to suppress tumour growth and increase survival in a medulloblastoma flank xenograft mouse model." (PMID 31492956, 2019). "This is of particular interest because medulloblastomas resistant to SMO inhibitors have been shown to activate the PI3K/AKT/mTOR pathway." (PMID 31492956, 2019). "Here, we sought to investigate the therapeutic effects of combined PI3Kα and mTOR inhibition in medulloblastoma and in particular the effects on the CSC population." (PMID 31492956, 2019). "We examined the effects of PI3Kα and mTOR inhibition on GLI1 nuclear accumulation in SHH-driven medulloblastoma using nuclear/cytoplasmic fractionation of DAOY cells with Lamin A/C and tubulin as nuclear and cytoplasmic loading controls, respectively." (PMID 31492956, 2019). "Together, these results suggest that catalytic mTOR inhibition strongly enhances the antineoplastic effects of selective PI3Kα inhibition in medulloblastoma cells." (PMID 31492956, 2019). "Pathways previously reported to be important in medulloblastoma were identified including the Ephrin B, mTOR, and integrin signaling pathways." (PMID 29880060, 2018). "MiR-182 inhibits apoptosis and promotes survival in medulloblastoma cells by regulating the PI3K/AKT/mTOR signaling axis." (PMID 28442995, 2017). "The miR-183-96-182 cluster regulates multiple biological programs that converge to support the maintenance and metastatic potential of medulloblastoma coupled to the PI3K/AKT/mTOR pathway." (PMID 27582688, 2016). "In initial studies, we sought to examine the effects of different mTOR inhibitors on the phosphorylation/activation of eIF4E in human medulloblastoma cells." (PMID 25193863, 2014). "Pharmacological targeting of Mnk1/2 or siRNA-mediated knockdown of Mnk2 sensitizes medulloblastoma cells to mTOR inhibition and promotes suppression of malignant cell proliferation and anchorage-independent growth." (PMID 25193863, 2014). "In studies in which the effects of combination therapies on anchorage-independent growth of Daoy medulloblastoma cells were assessed, we found enhanced effects by the combinations of mTOR and Mnk inhibitors." (PMID 25193863, 2014).
medulloblastoma (continued). "Taken together, these findings indicate that in both medulloblastoma lines, simultaneous inhibition of the mTOR and Mnk pathways results in substantially enhanced inhibition of anchorage-independent growth of malignant cells." (PMID 25193863, 2014). "Some targeted approaches may be explored in the context of MYC-amplified medulloblastoma and mTOR inhibitors." (PMID 39779613, 2025). "Based on existing evidence, targeting of MYC and mTOR pathways together produces functional synergy that could be the basis for effective therapies against medulloblastoma." (PMID 39779613, 2025). "MTOR is one of the major pathways known to be activated during medulloblastoma progression." (PMID 39779613, 2025). "This review updates recent findings on the crosstalk between MYC and mTOR and targeted therapies that inhibit both MYC and mTOR along with other treatment modalities that hold potential to treat the Group 3 MYC-amplified medulloblastoma at the translational level." (PMID 39779613, 2025). "Bioinformatic analysis of published datasets validated these pre-clinical findings, supporting a role for YB-1 in cell death and survival processes, cholesterol biosynthesis, response to therapeutics and MYC/mTOR signalling; as well as overall survival and metastasis in medulloblastoma patients." (PMID 36831428, 2023). "Resistance has been observed against mTOR inhibitor-targeted therapy in medulloblastoma." (PMID 35008889, 2021). "We report evidence for a discrete role of the PI3Kα/mTOR pathway in SHH subtype medulloblastoma." (PMID 31492956, 2019). "Importantly, pharmacologic mTOR inhibition greatly enhanced the inhibitory effects of alpelisib on medulloblastoma tumour growth in vivo." (PMID 31492956, 2019). "Pharmacological mTOR inhibition potently enhanced the suppressive effects of alpelisib on cancer cell proliferation, colony formation and apoptosis and additionally blocked sphere-forming ability of medulloblastoma stem-like cancer cells in vitro." (PMID 31492956, 2019). "Thus, dual PI3Kα and mTOR inhibition is a comprehensive strategy that includes targeting the CSC population and therefore shows promise for treatment of high-risk category medulloblastoma in different subgroups." (PMID 31492956, 2019). "In the present study, we sought to determine whether eIF4E phosphorylation accounts for resistance to mTORC1 inhibition in medulloblastoma cells and, if so, to investigate the mechanisms of cross-talk between the mTOR and Mnk pathways in medulloblastoma cells." (PMID 25193863, 2014). "Our data provide evidence for a unique Mnk2-mediated mechanism and suggest that combinations of mTOR and Mnk2 inhibitors may provide a therapeutic approach for human medulloblastoma." (PMID 25193863, 2014). "This suggests that inhibitors of the PI3K/mTOR pathway may be promising in combination therapies for certain medulloblastoma subgroups." (PMID 25193863, 2014). "Altogether, these findings provide evidence for the existence of a Mnk2-controlled feedback loop in medulloblastoma cells that accounts for resistance to mTOR inhibitors, and raise the potential for combination treatments of mTOR and Mnk inhibitors for the treatment of medulloblastoma." (PMID 25193863, 2014). "In subsequent studies, we sought to determine whether combined treatment of medulloblastoma cells with Mnk and mTOR inhibitors results in enhanced antineoplastic effects." (PMID 25193863, 2014). "Knockdown of the full cluster in medulloblastoma cells results in dysregulation of the PI3K/AKT/mTOR signaling axis and enhancement of genes related to apoptosis; thus, the miR-183/96/182 cluster again appears as an attractive target for potential therapeutic applications in MCC." (PMID 24627810, 2014). "To investigate whether the combination of mTOR and Mnk inhibition might be similarly effective in other medulloblastoma subgroups we extended our analysis by including D556 cells, which exhibit amplified MYCC." (PMID 25193863, 2014).